TNF (tumor necrosis factor)
Diseases named in the same sentence as TNF in open-access papers (continued):
Sharing a sentence is not in itself a finding about the gene and the disease.
hepatocellular carcinoma (continued). "Our results indicate that both the HCV TCR-transduced CD4+ and CD8+ T cells recognized the HCV NS3:1073–1081 peptide-loaded targets and HCV+ hepatocellular carcinoma cells (HCC) in a polyfunctional manner with cytokine (IFN-γ, IL-2, and TNF-α) production as well as cytotoxicity." (PMID 20686664, 2010). "IFN-γ remarkably increased TRIM21 in PHHs, and unlike in the hepatoma cell lines, TRIM21 levels were also increased by TNF-α." (PMID 38780244, 2024). "In rat hepatoma cells, treatment with interferon (IFN)-γ/tumor necrosis factor (TNF)-α/LPS triggers ·NO-mediated IRP1 activation without changes in IRP2, accompanied by the translational repression of Fn expression." (PMID 33419006, 2021). "Telbivudine stimulated TNFα and TGF-β1 secretion in human macrophagic U-937 cells but not in human hepatoma HepG2 cells." (PMID 31770396, 2019). "We also evaluated in Hep3B cells, a human hepatoma cell line, mRNA expression of A20 and of IL8, a chemokine induced by TNF in human cell types with no murine homolog." (PMID 27831566, 2016). "In hepatoma cell lines HepG2 and Huh7, TRIM21 was significantly increased by IFN-γ but not TNF-α." (PMID 38780244, 2024).
osteoporosis (404 papers, 1996 to 2026). A condition of reduced bone mass, with decreased cortical thickness and a decrease in the number and size of the trabeculae of cancellous bone (but normal chemical composition), resulting in increased fracture incidence. "Serum level of inflammatory factors, such as INF© and TNFα were significantly elevated in osteoporotic patients, which is associated with low bone mass and therefore an independent risk factor for osteoporosis." (PMID 41158755, 2026). "The polymorphism -308G>A in the promoter of the TNF-α is intensively studied as a potential screening and diagnostic biomarker of osteoporosis." (PMID 41141340, 2025). "Increasing evidence suggests that the TNF-α gene -308G>A (rs1800629) polymorphism is associated with an increased risk of osteoporosis and reduced BMD." (PMID 41141340, 2025). "SR’s anti-inflammatory properties further contribute to its anti-osteoporotic potential as it suppresses inflammatory cytokines TNF-α and IL-6, both of which are associated with bone resorption in osteoporosis." (PMID 40496246, 2025). "Previous studies have confirmed that M1 macrophages, in the context of osteoporosis and inflammatory bone loss, can facilitate osteoclastogenesis and bone resorption by secreting pro-inflammatory cytokines such as IL-1β and TNF-α." (PMID 41246341, 2025). "Monocytes that are overexpressed exhibit elevated levels of TNF-α and IL-6, which are associated with osteoporosis." (PMID 41158629, 2025). "First, sarcopenic obesity and osteoporosis are strongly associated with chronic low-grade inflammation, with pro-inflammatory cytokines such as IL-6, TNF-α, and IL-1 playing a critical role in developing both conditions." (PMID 40569474, 2025). "This pervasive inflammation is associated with an increased risk of osteoporosis, primarily due to the release of proinflammatory cytokines such as interleukin-1 (IL-1), interleukin-6 (IL-6), and tumor necrosis factor-alpha (TNF-α)." (PMID 39866531, 2025). "Previous studies have shown elevated levels of TNF-producing T cells and IL-17 in women with osteoporosis, both of which are associated with increased bone loss." (PMID 41140653, 2025). "Inflammatory cytokines, such as tumour necrosis factor α (TNF‐α), inhibit osteogenic differentiation of bone marrow mesenchymal stem cells (BMSCs), and several microRNAs are implicated in osteoporosis development." (PMID 38748896, 2024). "In osteoporosis, pro-inflammatory cytokines, such as IL-1, IL-6, IL-1β, and TNF-α, have been positively correlated with periodontal bone loss." (PMID 39410587, 2024). "TNFα, IL-6, and IL-1 have been linked to the formation of osteoclasts in osteoporosis patients and animal models of ovariectomy." (PMID 37239124, 2023). "Inflammatory cell-induced cytokines, including matrix metalloproteinases, IL-6, IL-17, osteoprotegerin, and TNF-α, have been strongly associated with the development of osteoporosis." (PMID 37240965, 2023). "TNF-α and IL-6 are closely related to the function of osteoclasts, and the high expression of inflammatory factors is a risk factor for osteoporosis." (PMID 36766210, 2023). "Activation of inflammatory factors associated with osteoporosis such as TNF-α, NF-κB, IL-1, IL-6, and IL-17 has been to be involved in the physiology of pro-osteoclast formation." (PMID 36967748, 2023). "Such an association of GSs and osteoporosis arises possibly, among other things, due to increased immune inflammation and secretion of pro-inflammatory interleukins (IL-1, IL-6) and TNF." (PMID 36780036, 2023). "Postmenopausal osteoporosis, primarily attributed to estrogen deficiency, leads to the production of pro-osteoclastogenic cytokines like TNFα and RANKL." (PMID 38298188, 2023). "For example, isoflavones have been shown to reduce the risk of osteoporosis by decreasing the expression of main protein factors that regulate bone metabolism, such as tumor necrosis factor-α and interleukin-6, which activate osteoclasts." (PMID 37049447, 2023).
osteoporosis (continued). "TNF-α/NF-κB is a well-known inflammatory signaling pathway that is implicated in the development of endocrine system illnesses, particularly osteoporosis." (PMID 36967748, 2023). "Polymorphisms of genes such as VDR, ER, OPG, COL1A1 and TNFα are associated with osteoporosis and fracture risk." (PMID 36362662, 2022). "As a major etiological factor for osteoporosis, estrogen deficiency favors the release of proinflammatory cytokines, particularly TNF-α, leading to preosteoclast production and bone resorption." (PMID 35764967, 2022). "EGCG up-regulates TUG1 to inhibit the Hippo/YAP pathway activity caused by TNF-α and to improve biological functions of MC3T3-E1 cells, suggesting EGCG can effectively alleviate TNF-α-caused adverse effects in osteoporosis." (PMID 35358011, 2022). "Actually, high serum concentrations of the inflammatory cytokines IL-6 and TNF-α have been associated with osteoporosis." (PMID 34842966, 2022). "In osteoporosis models, elevated pro-inflammatory cytokines, including IL-6, IL-1 and TNF-α can induce bone loss by regulating osteoclastic differentiation and activation both directly and indirectly." (PMID 34917622, 2021). "LP alleviates osteoporosis by suppressing NF-κB-linked TNF-α expression and alleviates gut inflammation, which improves osteoporosis." (PMID 33805153, 2021). "The pathogenesis of osteoporosis involves TNF-α and anti-TNF biologics are able to block generalised bone loss in arthritides." (PMID 34556105, 2021). "Animal models also supported the pathological role for inflammation in osteoporosis as both TNF and TNF receptor 1 deficient mice present resistance to ovariectomy-induced bone loss." (PMID 34917622, 2021). "Factors affecting osteoporosis and fracture risk due to direct effects on bones, such as anti-TNF agents, bisphosphonate, and autoantibody positivity, werealso different." (PMID 34209074, 2021). "Growing evidences have confirmed that miRNAs were involved in the regulation of bone turnover by TNF-α in estrogen deficiency-induced osteoporosis." (PMID 33425899, 2020). "The mechanisms of osteoporosis associated with RA involve the influence of inflammatory cytokines, such as interleukin (IL)-1, IL-6, and tumor necrosis factor (TNF); glucocorticoid treatment; and immobility." (PMID 32555299, 2020). "A recent study reported that I-BET151 inhibited RANKL-induced osteoclastogenesis and bone loss in post-ovariectomy osteoporosis, inflammatory arthritis, and TNF-induced osteolysis mouse models by targetting MYC-NFAT axis." (PMID 30455393, 2019). "Our data suggest that the interaction of the CG/CC genotype of VDR rs3782905 with TNF-α rs1800629 GG genotype is associated with increased risks of overall and lumbar spine osteoporosis among elderly women." (PMID 31887189, 2019). "The mechanism underlying DANCR-IL-6/TNF-α link should be further dissected, and explored for new osteoporosis treatments." (PMID 30937214, 2019). "IL-1, IL-6 and TNF-α are strong inducers of bone resorption and subjects with highly expression of these cytokines are susceptible to develop osteoporosis." (PMID 30717716, 2019). "The severe osteoporotic phenotype in Tg5519 was further aggravated, while mild osteoporosis in Tg5516 mice converted to severe osteoporosis upon huTNF expression, indicating that TNF and RANKL also cooperate in systemic bone loss." (PMID 30804932, 2019). "On the contrary, we found that VDR rs3782905 polymorphism is interactive with TNF-α rs1800629 on overall and lumbar spine osteoporosis." (PMID 31887189, 2019). "In vivo experiments indicated that EXD treatment attenuated bone loss and decreased TNF-α levels in rats with osteoporosis." (PMID 31551787, 2019). "Another study showed that IFN-γ and tumor necrosis factor alpha synergistically induced MSC deficiency resulting in osteoporosis." (PMID 30305140, 2018).
osteoporosis (continued). "According to our previous work basis, the main pathogenic mechanism underlying estrogen deficiency-induced osteoporosis is excessive pro-inflammatory cytokines, such as TNF-α and INF-γ, which is primarily due to the increase of the total T-cell population." (PMID 29581449, 2018). "Osteoporosis is associated with inflammation and production of inflammatory cytokines including tumor necrosis factor-alpha (TNF-α), interleukin- (IL-) 6, and IL-1, which stimulate osteoclast activity." (PMID 27746822, 2016). "Several cytokines such as TNF-α, IL-1β, and IL-6 were implicated in the pathogenesis of osteoporosis." (PMID 23936022, 2013). "In studies conducted on healthy postmenopausal women, estrogen deficiency was demonstrated to cause osteoporosis by locally stimulating interleukin-1 (IL-1), IL-6, and tumor necrosis factor-α (TNF-α) synthesis." (PMID 23097664, 2012). "Inflammatory cytokines, including IL-1β, IL-6 and TNF-α, are also responsible for the characteristic loss of bone density in osteoporosis through their effect on osteoclast activity." (PMID 22176920, 2011). "The cytokines IL-1, IL-6 and TNF-α have been shown to regulate bone and evidence from animal models has suggested that these cytokines are associated with the development of osteoporosis through stimulation of osteoclastogenesis and subsequent bone resorption." (PMID 22254049, 2010). "This study indicates that TNF-a inhibition controls bone loss related to generalized osteoporosis within the context of RA." (PMID 17597527, 2007). "Osteoporosis has been linked to changes in gut microbiota, particularly a reduction in Lactobacillus species and an increase in pro-inflammatory cytokines such as TNF-α, IL-6, and IL-14 in the serum." (PMID 40422878, 2025). "However, administration of 1G244 attenuated this elevation, resulting in decreased levels of TNF-α, IL-23, and IL-23, which plays a role in immune regulation and bone loss in chronic inflammatory diseases like osteoporosis." (PMID 39968082, 2025). "The association between DANCR, IL-6, and TNF-α in osteoporosis therapies remains under examination." (PMID 41158629, 2025). "Furthermore, in cases where osteoporosis is induced by estrogen deficiency, tumor necrosis factor-alpha (TNF-α) has been shown to hinder MSC differentiation and bone formation." (PMID 37728585, 2024). "A retrospective analysis suspected that TNF-α inhibitor therapy in post-menopausal/estrogen-deficient patients could prevent osteoporosis but further studies are needed for clarification of the impact of TNF-α inhibitors." (PMID 37568441, 2023). "For instance, it was demonstrated that patients with herpes zoster infections presented with a 4.55-fold greater risk of osteoporosis, as associated with significantly high levels of interleukin (IL)-1b, IL-6, IL-8, IL-10, and tumor necrosis factor-alpha (TNF-α)." (PMID 37113002, 2023). "Pro-inflammatory cytokines such as TNF-α and IL-6 are among the high-risk factors in osteoporosis." (PMID 36673366, 2023). "TNFα has been shown to play an important role in estrogen deficiency-mediated osteoporosis." (PMID 36983039, 2023). "Bone loss (osteoporosis and bone erosion) is caused by increased osteoclast activity, although the link between TNF-inhibitory therapy and osteoclast activity has been debated; however, most findings indicate that TNF-inhibitory therapy leads to the inhibition of osteoblast differentiation." (PMID 36564778, 2022). "Moreover, the elevated bone fracture risk, osteoporosis, and osteopenia were studied and confirmed to be present in chronic inflammatory disorders, due to the action of inflammation factors (such as IL-6, TNF, and IL-1β)." (PMID 35334519, 2022). "Therefore, it is likely that H. pylori increases the risk of osteoporosis by promoting an inflammatory response to produce proosteoclastogenic cytokines such as TNFα, IL-1, IL-6, and IL-8." (PMID 35418807, 2022).
osteoporosis (continued). "Osteoporosis caused by ovariectomy was not only mediated by overactivated osteoclast activity but inflammation, serological results indicated that dimemorfan also reduced IL‐1β, IL‐6, and TNF‐α secretion." (PMID 35611810, 2022). "In elderly women, we found that those carrying the CG/CC genotype of VDR rs3782905 were significantly associated with increased odds of overall osteoporosis compared with those carrying the GG genotype of VDR rs3782905 among those carrying TNF-α rs1800629 GG genotype." (PMID 31887189, 2019). "Given that inflammation is one of the most important causes of osteoporosis, we tested whether TNF-α treatment could mimic the inflammatory microenvironments." (PMID 29167750, 2017). "IL-1β and TNF-α were positively associated with NTx in osteoporosis women." (PMID 28121926, 2017). "It has been demonstrated that increased levels of interleukin-1 and TNF-α can lead to bone resorption and, therefore, may increase the risk of osteoporosis." (PMID 24959176, 2014). "Estrogen, a potent endocrine hormone linked to osteoporosis, has been demonstrated to bind osteoblastic cells and suppress the expression of several paracrine proosteoblast factors including interleukin-1 (IL-1), IL-6, and tumor necrosis factor-α (TNFα)." (PMID 24286015, 2013). "In fact, tumor necrosis factor a (TNF-α) and interleukin-6 (IL-6) have been reported to be associated with osteoporosis in COPD patients, and both factors are known to stimulate osteoclasts and increase bone resorption through RANKL-mediated bone resorption in vitro." (PMID 22360380, 2012). "In conclusion, our study demonstrated that quercetin could rescue TNFα-impaired BMSCs osteogenesis in vitro and osteoporosis-induced bone loss in vivo, in a Malat1-dependent manner, suggesting that quercetin may serve as a therapeutic candidate for osteoporosis treatment." (PMID 36983039, 2023). "TNF inhibition may also affect arthritis-associated osteoporosis." (PMID 34556105, 2021). "Hence, it is speculated that TNF-α-induced osteoblast apoptosis might be responsible for bone loss, resulting in osteoporosis." (PMID 32400849, 2020). "Although the sample size of this study may have been relatively small, our results suggest that the interaction of the CG/CC genotype of VDR rs3782905 with TNF-α rs1800629 GG genotype was associated with increased odds of overall and lumbar spine osteoporosis in elderly women." (PMID 31887189, 2019). "Therefore, dysregulation of the TNFα-Ptgs2-Bcl2 pathway might be a cause of the bone loss and osteoporosis observed in SMA patients." (PMID 27331400, 2016). "Additionally, in estrogen deficiency-associated osteoporosis, TNF-α was found to be notably overproduced and may induce bone loss due to its biphasic effects in the promotion of bone resorption and reduction of bone formation." (PMID 25816130, 2015). "In the Geelong osteoporosis study (GOS), TNFα explained the association between muscle density measured in the radius and psychomotor function, but the mediation was not established for the muscle density measured in the tibia." (PMID 39974123, 2025). "In the prospective clinical cohort, we observed a clear dose-response relationship, with IL-1β, IL-6, and TNF-α levels showing significant graded increases across the control, osteopenia, and osteoporosis groups." (PMID 41451124, 2025). "Quercetin upregulates Wnt/β-catenin signaling while inhibiting NF-κB signaling, thereby restoring osteogenesis in MSC compromised by TNFα-induced osteoporosis." (PMID 41226117, 2025). "Oxidative stress is a robust inducer for the expression of pro-resorptive cytokines such as IL-1, TNF-α, and IL-6, culminating in osteoporosis." (PMID 39780225, 2025). "In conclusion, PGRN attenuates TNFα‐induced osteoporosis by interacting with TNFR1 and promotes osteoblast genesis by interacting with TNFR2." (PMID 39910695, 2025).